INS (insulin)
Diseases named in the same sentence as INS in open-access papers (continued):
Sharing a sentence is not in itself a finding about the gene and the disease.
type 2 diabetes (continued). "Insulin resistance, excessive or improper glucagon secretion, and insufficient insulin secretion are symptoms of type 2 diabetes mellitus (T2DM), a chronic endocrine metabolic disorder." (PMID 36419826, 2022). "Importantly, the beneficial anti-diabetic effects of A. muciniphila have also been studied in humans more recently, revealing links between the decreased abundance of the organism and impairment of insulin secretion and glucose homeostasis, specifically in lean individuals with type 2 diabetes." (PMID 36361709, 2022). "BG monitoring remains a mainstay of management in people with type 2 diabetes (T2DM) who take sulphonylurea (SU) drugs or insulin." (PMID 34921531, 2022). "Thus, it is intriguing to speculate that cardiac insulin resistance may act beyond changes in the plasma glycemic state during the development of type 2 diabetes-accelerated atherosclerosis." (PMID 35328064, 2022). "We conducted the safety sub-study of the Memory Advancement by Intranasal Insulin in Type 2 Diabetes (MemAID) studying INI therapy in participants with T2DM on systemic insulin." (PMID 35903156, 2022). "Moreover, it could be the indicator for insulin requirements for appropriate glycemic control in type 2 diabetes." (PMID 35229479, 2022). "The aim of this population-based cohort study was to assess the impact of insulin treatment on cancer incidence in subjects with type 1 (T1DM) or type 2 diabetes (T2DM) in Italy." (PMID 35681699, 2022). "In addition, Cr3+ complexes have been used to treat type 2 diabetes as insulin amplifiers." (PMID 35782923, 2022). "Type 2 diabetes (T2DM) is a chronic metabolic disease characterized by abnormal insulin secretion or defective insulin action." (PMID 35237647, 2022). "NaHS-treated mice exhibited a reduced body weight gain ratio, serum triglyceride, blood glucose, and serum insulin, thereby suggesting that the NaHS treatment manner in this study may also act as a beneficial function in the context of obesity and type 2 diabetes." (PMID 35425717, 2022). "Estrogens influence metabolism by improving body weight and fat tissue control, insulin sensitivity (IS) and glucose tolerance, protecting females from diet-induced obesity, liver steatosis and type 2 diabetes mellitus (T2DM)." (PMID 35743689, 2022). "Type 2 diabetes (T2D) is characterized by high blood glucose levels and develops due to inadequate pancreatic β-cell function (i.e., insulin secretion) in the face of peripheral insulin resistance." (PMID 35053407, 2022). "In a 6-month randomized controlled trial, Brennan and colleagues investigated the effects of caloric restriction-induced weight loss with and without exercise on insulin sensitivity in physically inactive older obese adults with or at high risk for type 2 diabetes." (PMID 35834023, 2022). "Results demonstrated that treadmill running delayed the progression of type 2 diabetes by up-regulating the proliferation and morphology of beta-cells, short-duration low-intensity wheel running improved islet failure by ensuring insulin mRNA and insulin storage." (PMID 35742478, 2022). "Type 2 diabetes mellitus (T2DM) is a metabolic disease characterized by hyperglycemia resulting from insulin resistance and insufficient insulin secretion by pancreatic β-cells." (PMID 35755256, 2022). "Non-O blood groups are associated with decreased insulin sensitivity and risk of type 2 diabetes." (PMID 36144194, 2022). "Both the PI3K/AKT pathway and MAPK pathway were marked as significant pathways in our network pharmacology analysis, which suggested that BHHD could directly regulate INS-related pathways, such as FoxO signalling pathway, INS resistance, type II diabetes, and INS signalling pathway." (PMID 35600955, 2022).
type 2 diabetes (continued). "Our study was specifically focused on pediatric patients with T1D using CGMs; hence, our findings may not be generalizable to other populations, such as adults with T1D or children with type 2 diabetes or to explore outcomes for patients with insulin pumps or automated insulin dosing systems." (PMID 36265838, 2022). "Moreover, inadequate insulin sensitivity often leads to type 2 diabetes." (PMID 35565811, 2022). "miRBase analysis showed that identified FGL1 3′UTR mutations may affect miRNA binding sites previously reported as correlated with obesity, including those involved in the insulin signaling pathway, maturity-onset diabetes of the young, type II diabetes mellitus, and adipocytokine signaling pathway." (PMID 36011329, 2022). "Indeed, in noninsulin-dependent diabetes, there is insulin sensitivity, which leads to hyperinsulinism and elevated circulating levels of insulin-like growth factors (IGFs) that are capable of stimulating cell proliferation in many organs, in particular the liver, pancreas, colon, ovary, and breast." (PMID 36277886, 2022). "During the early stage of type 2 diabetes mellitus (T2DM), the synthesis and secretion of insulin by islet β-cells are enhanced, coupled with endoplasmic reticulum (ER) stress, and alterations in the management of lipid metabolism." (PMID 36005626, 2022). "There is an increasing recognition that early-life undernutrition could lead to smaller beta cell mass and insulin secretion defects demonstrable from early childhood in serially studied birth cohorts and could manifest as prediabetes or type 2 diabetes in young adulthood." (PMID 34689214, 2022). "In addition, considering the association of LD formation and autophagy LD accumulation may be accelerated by altered autophagy of immature or old insulin granules in type 2 diabetes, probably resulting in decreased mature insulin granules." (PMID 36204103, 2022). "The association between tuberculosis (TB) and type 2 diabetes mellitus (T2D) has been known for centuries but disappeared from the literature after the 1950s with the advent of insulin to treat T2D and discovery of effective first-line anti-TB drugs." (PMID 36558885, 2022). "Type 2 diabetes mellitus (T2DM) has become a serious public health problem across the globe, which is typically characterized by impaired insulin secretion and insulin resistance, and seriously affects the quality of life of patients." (PMID 35813055, 2022). "Studies of regular exercise training for ≥8 weeks have shown improvements in insulin sensitivity and glycemic control, together with beneficial changes in cardiorespiratory fitness (VO2max), body composition, blood pressure, and lipid profile in patients with type 2 diabetes." (PMID 36387850, 2022). "Type 2 diabetes mellitus (T2DM) is a metabolic disease characterised by hyperglycaemia, insulin resistance and insufficient insulin secretion." (PMID 36248844, 2022). "However, if patients living with type 2 diabetes, medications include oral medications to control it, while others may also need insulin." (PMID 35123455, 2022). "As a result, elucidating the mechanisms underlying this type of intermittent fasting and exercise therapy‐related improved insulin sensitivity could help researchers to better understand how insulin sensitivity develops in conditions like obesity and type 2 diabetes." (PMID 36305681, 2022). "This may result in impaired insulin release and hyperglycaemia, developing type 2 diabetes." (PMID 35205066, 2022). "The relationships of gastric emptying (GE) with the glycemic response at 120 minutes, glucagon-like peptide-1 (GLP-1), and insulin secretion following a glucose load in type 2 diabetes (T2D) are uncertain." (PMID 35608823, 2022). "The results demonstrated that YA could increase insulin levels in mice with type 2 diabetes." (PMID 35740008, 2022).
type 2 diabetes (continued). "Similarly, in the streptozotocin (STZ)-induced type 2 diabetes rat model, Dio1 activity and mRNA expression level in rats recoved to control levels after administration of T3 treatment and increased significantly when T3 and insulin were co-administrated." (PMID 36605939, 2022). "It regulates energy balance, increases adipocyte Uncoupling Protein-1 (UCP1) expression, improves insulin sensitivity, and contains the spread of variable metabolic diseases, including obesity, type 2 diabetes mellitus (T2DM), and hypertension." (PMID 35094663, 2022). "An improvement of the insulin secretory capacity in patients with type 2 diabetes is a therapeutic goal that is difficult to achieve non-pharmacologically, and only a few studies in patients with type 2 diabetes have reported improvements in β-cell secretion following physical training." (PMID 36531168, 2022). "Type 2 diabetes mellitus (T2DM) is characterized by insulin resistance, hyperglycemia, and relative impairment in insulin secretion." (PMID 35340218, 2022). "Previously, we have demonstrated that the skeletal muscle insulin resistance in obesity and type 2 diabetes associates with activation of the myocellular diacylglycerol (DAG)–novel protein kinase C (nPKC) isoform θ pathway, an inhibitory cascade of proximal insulin signalling." (PMID 34704121, 2022). "Thus, ASCs from high-fat diet and streptozotocin-induced type 2 diabetes had inferior proliferative capacity compared to cells from healthy controls, improved insulin sensitivity and less β cell death was seen in T2D mice receiving mesenchymal stem cell therapy." (PMID 35163613, 2022). "DMR, when combined with a glucagon-like peptide-1 receptor agonist (GLP-1RA), resulted in discontinuation of exogenous insulin treatment in 69% of patients with insulin dependent type 2 diabetes mellitus (T2DM) in the INSPIRE study." (PMID 36992788, 2022). "In type 2 diabetes mellitus (T2DM), insulin resistance and defective insulin release are often accompanied by increased glucagon levels, which further mobilize glucose from the liver." (PMID 36104518, 2022). "Additionally, insulin clearance, increasingly recognized as an independent risk factor for type 2 diabetes, was not investigated in this study." (PMID 35133989, 2022). "Thus, MMPP, as a PPARγ agonist, may be a potential drug for type 2 diabetes and metabolic disorders, which may help increase adipogenesis and insulin sensitivity." (PMID 36339572, 2022). "However, structurally defined PIGs as true small-molecule insulin mimetics could be of value for the therapy of diabetes mellitus type II." (PMID 35806423, 2022). "Understanding insulin action and resistance more completely will facilitate the intelligent use of existing anti-diabetic therapies, enable the development of new therapeutics, and perhaps most importantly, inform prevention strategies to stem the tide of type 2 diabetes." (PMID 35455055, 2022). "The high AIDPS group was remarkably enriched for digestive and metabolism-related pathways, such as insulin secretion and regulation, peptide hormone secretion and regulation, fat digestion and absorption, pancreatic secretion, maturity onset diabetes of the young, and type II diabetes mellitus." (PMID 36282174, 2022). "All this information could provide new insight into insulin-resistant type 2 diabetes development." (PMID 36009412, 2022). "Moreover, it has been shown that cross-seeding between Aβ and amylin or insulin may explain the link between type 2 diabetes (T2D) and AD." (PMID 36551314, 2022). "This supports the notion that reducing inflammatory processes, as measured by CRP, in addition to lowering insulin levels and improving insulin sensitivity, could contribute to protective effects against development of type 2 diabetes and progression of cardiometabolic disease." (PMID 36467859, 2022).
type 2 diabetes (continued). "Type 2 diabetes mellitus (T2DM) is a metabolic disorder with multiple causes, represented by chronic hyperglycemia and carbohydrate, lipid and protein metabolism disorders associated with insulin resistance, the progressivity of which may also affect insulin secretion defects or combinations." (PMID 35209015, 2022). "This might be because poor physical exercise can impede the rapid enhancement of skeletal muscle oxidative capacity, insulin sensitivity, and glycemic control in diabetic patients, particularly patients with type 2 diabetes, resulting in worsening ocular complications." (PMID 36227943, 2022). "In addition, most people with type 2 diabetes ultimately need insulin therapy." (PMID 36292529, 2022). "GHB’s capacity to protect the insulin-producing ß-cells of the pancreas from the toxic effects of high plasma levels of fatty acids may open the door to further investigation of this or related compounds as adjuvants in the treatment of type 2 diabetes." (PMID 35159354, 2022). "In another study, irisin improved glucose tolerance while reducing serum insulin levels in a rat model of type 2 diabetes mellitus (T2D)." (PMID 35203466, 2022). "Long-acting insulin analogs such as insulin glargine will consistently remain at a relatively low level for a rather long period; therefore, interference of endogenous insulin makes sense in clamp studies conducted in patients with type 2 diabetes or the healthy people." (PMID 35250591, 2022). "Thus, β-cell defects such as impaired autocrine feedback through Insr may contribute to insulin hypersecretion and accelerate the early stages of type 2 diabetes." (PMID 35136059, 2022). "Obese patients with WAT-IR have increased insulin-secreting beta-cell dysfunction, a precursor to Type 2 diabetes mellitus (T2D)." (PMID 35456015, 2022). "However, in the recent population-based KORA-Age study which included 118 older people with type 2 diabetes, mean (SD) age 74.6 (6.2) years, insulin therapy was associated with preserved muscle mass, but not muscle function parameters." (PMID 35723859, 2022). "Type 2 diabetes (T2D) is a serious chronic disease characterised by dysregulated insulin secretion and activity, leading to increased levels of glucose in the bloodstream." (PMID 35631264, 2022). "There is a wealth of data on the preventive or delaying effect of physical activity against type II diabetes, and a wealth of data is available on the molecular mechanism underpinning exercise- and insulin-induced glucose uptake and its relation to type II diabetes." (PMID 36148310, 2022). "A large weight loss (14%–30%) achieved through gastric bypass surgery is known to improve insulin secretory capacity in patients with type 2 diabetes, but to our knowledge, this is the first study to demonstrate that even a small weight loss achieved via ADF may have the same effect." (PMID 36531168, 2022). "Glycemic dysregulation might reflect poor pancreatic β-cell function and the inadequate release of endogenous insulin; therefore, hyperglycemia and high GV would be more pronounced in patients with type 2 diabetes with worse glucose control and longer disease duration." (PMID 36575485, 2022). "Therefore, when anti-CD38 antibodies are present in patients, glucose-induced insulin secretion could be impaired and result in type 2 diabetes." (PMID 35457121, 2022). "In patients with type 2 diabetes, over 29 days, body weight was reduced by up to 3 kg, fasting plasma glucose was reduced by up to 3 mmol/l, plasma glucose following an oral glucose load was dose-dependently reduced, while insulin secretory responses were dose-dependently increased." (PMID 36050763, 2022). "However, we found that blood glucose did not decrease but increased rapidly after insulin injection in the control group and orlistat group, which is consistent with the characteristics of type 2 diabetes caused by obesity." (PMID 35269668, 2022).
type 2 diabetes (continued). "Here, we chose a 10 h TRE, which we believe would be feasible to incorporate into the work and family life of most adults with type 2 diabetes; future studies will be needed to reveal whether the duration of the fasting period is indeed crucial in determining positive effects on insulin sensitivity." (PMID 35871650, 2022). "Type 2 diabetes mellitus (T2DM) patients who have mutations of KCNH2 caused long QT syndrome (LQTS) and increasing insulin secretion." (PMID 36325440, 2022). "Type 2 diabetes mellitus (T2DM) is a complex metabolic disease characterized by hyperglycemic states resulting from tissue insulin resistance." (PMID 36139749, 2022). "A review reported that whey proteins, rich in branched-chain amino acids (BCAAs) such as leucine, isoleucine, valine, and lysine may decrease postprandial glucose responses and stimulate insulin secretion in healthy individuals and patients with type 2 diabetes." (PMID 36153548, 2022). "Insulin-secreting pancreatic β cells can be impaired by autoimmune processes mediated via macrophages, cytokines, and T cells weaken them in type 1 diabetes and by oxidative stress, elevated lipid or glucose levels, and inflammatory mediators in type 2 diabetes." (PMID 36557843, 2022). "Interestingly, type 2 diabetes is characterised by an impaired insulin-stimulated glycogen storage." (PMID 35871650, 2022). "The objective, of another recently published experimental study, was to investigate the effects of metformin on gut microbiota and compared it with insulin treatment in rats with type 2 diabetes mellitus (T2DM)." (PMID 35203519, 2022). "Type 2 diabetes mellitus (T2DM) is a complex metabolic disease mainly characterized by hyperglycemia arising from insulin resistance and/or insufficient insulin secretion." (PMID 35733117, 2022). "However, it is essential to note that exclusively insulin therapy (Basal + rapid or short-acting insulins) is prescribed for advanced type 2 diabetes patients when monotherapy, dual oral therapy, oral therapy and Insulin regimens in combination with oral medications fail." (PMID 36581933, 2022). "The risk of hypoglycemia is a barrier to optimal treatment of type 1 diabetes (T1DM) and type 2 diabetes (T2DM), especially in the context of insulin therapy, making blood glucose control optimization challenging." (PMID 36318542, 2022). "In addition, KEGG pathway analysis of the DEGs showed enrichment for terms associated with maturity-onset diabetes of the young (MODY) and insulin secretion, implicating that loss of TETs impairs pancreatic endocrine formation at later stages of endoderm specification." (PMID 35798741, 2022). "This is expected as existing knowledge about type 2 diabetes; namely, developing type 2 diabetes doesn’t mean that the body cannot produce insulin (such like type I diabetes, which is an autoimmune disease; the immune system attacks the pancreas, so it can’t make insulin)." (PMID 35778708, 2022). "In addition, insulin is closely related to the function of photoreceptor cells, such that both absolute and relative deficits in insulin, which are crucial features of type 1 and type 2 diabetes, respectively, could influence photoreceptor cells." (PMID 36362154, 2022). "Due to the central role in insulin secretion, the potassium inwardly-rectifying channel subfamily J member 11 (KCNJ11) gene is one of the essential genes for type 2 diabetes (T2D) predisposition." (PMID 36456687, 2022). "For patients with type 2 diabetes mellitus (T2DM), most antidiabetic drugs (ADs) other than insulin (i." (PMID 36094919, 2022). "However, unlike older people, younger people with type 2 diabetes tend to suffer more from insulin deficiency, whereas older people tend to be more insulin resistant." (PMID 35057569, 2022).